ENSG00000201500
Synonyms: LOC124903419
Gene: Small nucleolar RNA gene on chromosome 14 (100,977,389 to 100,977,466, forward strand). Ensembl gene ENSG00000201500.
Gene Ontology:
Biological process: RNA processing
Cellular component: nucleolus
Homologues: Paralogues in human: SNORD114-14 (65% identical), SNORD114-3 (65% identical), SNORD114-21 (64% identical), SNORD114-1 (62% identical), SNORD114-11 (62% identical), SNORD114-15 (62% identical), SNORD114-17 (62% identical), SNORD114-2 (62% identical), SNORD114-12 (60% identical), SNORD114-18 (60% identical), SNORD114-22 (60% identical), SNORD114-23 (60% identical), and 27 more.